MAPK14 (mitogen-activated protein kinase 14)
Diseases named in the same sentence as MAPK14 in open-access papers (continued):
Sharing a sentence is not in itself a finding about the gene and the disease.
tumor (continued). "In addition, cells that over-expressed CRN5 showed an activation of the MAPK14 pathway suggesting an involvement of CRN5 in tumour progression via the MAPK14 signalling pathway." (PMID 26373535, 2015). "Moreover, we linked coronin 2A to MAPK14 and PRMT5 signalling pathways involved in tumour progression." (PMID 26373535, 2015). "Although our goal in this study was to study the effect of BMP7 on immune cells in the tumor microenvironment, the downregulation of MAPK14 by BMP7 in resistant tumors cells might also be an important mechanism of resistance to immunotherapies that deserve further investigation." (PMID 32973129, 2020). "In order to determine whether MAPK14 downregulation in TILs depended on BMP7 secretion in the tumor microenvironment, we evaluated the expression of MAPK14 and MAPK14-regulated cytokines and chemokines in TILs isolated from BMP7-knockdown tumors and control tumors treated with IgG or anti-PD1." (PMID 32973129, 2020). "In the context of anticancer drug discovery, the MAPK14 (p38α), a protein in the MAPK cascade, has a wide array of functions in cell cycle regulation, proliferation, tumor aggressiveness, and cell death." (PMID 38727308, 2024). "MAPK14 belongs to the mitogen-activated protein kinase (MAPK) family of proteins, enhancing the formation of tumor platelet aggregates that interact with lung endothelium to form lung metastases." (PMID 37999247, 2023). "Based on the TCGA database, we plotted a box diagram of MAPK14 and ERBB3 expression for tumor tissues and adjacent normal samples." (PMID 37537191, 2023). "The expression of MAPK14, a negative regulator of pre-adipocyte adipogenesis, was increased when MDA-MB-231-LKB1 was seeded on the adipose and tumor scaffolds." (PMID 35755802, 2022). "MAPK14, commonly referred to as p38α MAPK, was proven to strengthen the formation of tumor-platelet aggregates that interact with the lung endothelium to form pulmonary metastases." (PMID 35356244, 2022). "We next investigated if tumor-secreted BMP7 regulates IL1A, IL1B, TNF, and CCL5 via MAPK14 in macrophages." (PMID 32973129, 2020). "Sorafenib is an oral, small molecule inhibitor of multiple tyrosine kinase receptors involved both in angiogenesis and tumour cell proliferation: VEGFR-2, VEGFR-3, PDGFR-β, RAF kinase, FLT3, KIT, p38 MAP kinase (p38-alpha, MAPK14)." (PMID 17519900, 2007). "MAPK14 and SYK play important roles in inflammation activation and signal transduction and may inhibit tumor cell proliferation by mediating pyroptosis." (PMID 41008944, 2025). "While p38α/MAPK14 isoform has been most extensively studied, p38δ/MAPK13 has recently emerged as a potential drug target because of its roles in stress responses, cytokine production, and tumor development." (PMID 37599001, 2023). "For example, ATM regulates radiation-induced autophagy through the mTOR pathway, MAPK14 pathway, JNK pathway, and PI3KIII pathway, and complete lack of ATM function results in the failure of autophagy induction in tumor cells or switches the cell stress response to senescence." (PMID 35888608, 2022). "In this scenario, co-upregulation of MAPK14 (together with ATF2) might enable the competitive edge for MAPK14- as compared to ATM-mediated ATF2 activation, thereby driving tumor progression and drug resistance." (PMID 33803354, 2021). "Upon phosphorylation by MAPK14, ATF2 can function as a tumor promotor." (PMID 33803354, 2021). "A significant correlation was found between expression levels of NORAD and MAPK14 in tumor tissues but not in ANCTs." (PMID 32433496, 2020).
tumor (continued). "After 4 weeks, it was found that the tumor size and weight in MAPK14 knockdown group were significantly lower than those of vector group, while in CDC25B overexpression group, the tumor size and weight were significantly higher than those of the vector group (P < .05)." (PMID 31856414, 2020). "Moreover, activation of the MAPK14 signaling pathway has been previously shown to correlate with poor prognosis in GBM patients, increased tumor invasiveness, and aggressive phenotype." (PMID 33021050, 2020). "Paired analysis of matched normal‐tumor samples confirmed this pattern for MAPK14 but not CDC42." (PMID 41246859, 2025). "In the present study, DRD2 knockout mice were selected as the model, and inhibition of MAPK14 reduced the secretion of PRL and growth of tumor, suggesting that DRD2 activation is not the only means of regulation of expression of PRL." (PMID 32894113, 2020).
infection (55 papers, 2008 to 2026). The state of being infected such as from the introduction of a foreign agent such as serum, vaccine, antigenic substance or organism. "It is well known that MAPK14 (also known as protein kinase p38α) is a member of the mitogen-activated protein kinase family that is activated by environmental and endogenous physiological stimuli associated with tissue injury and infection." (PMID 38974913, 2024). "Differential regulation of CASP8 and MAP2K3, two genes involved in the activation of MAPK14/p38, was observed, which could explain differences in the pro-inflammatory responses observed after infection with highly and less pathogenic ASFV isolates." (PMID 36298696, 2022). "A179L, therefore, might also be involved in inhibiting effects induced in response to MAPK14/p38 activation during the early times of infection." (PMID 36298696, 2022). "Simultaneously, the expression of MAPK14 was found significantly downregulated after infection." (PMID 35046920, 2021). "Contrary to that, expression levels of MAPK14 and RIPK1 were significantly reduced at 24h after infection with any of the viruses." (PMID 36298696, 2022). "We next analyzed the protein-protein interaction network even further and demonstrated that the infection related proteins STAT3, AKT1, MAPK9, MAPK14, and CREBBP had the highest degree of connectivity among DAPs." (PMID 36262184, 2022). "In the post-infection phase at three and ten months, there was persistent protein underexpression of pathways essential for cellular function, signaling, and homeostasis (AKT1, MAPK14, HSPB1)." (PMID 39324144, 2024). "Also, the STAT3, AKT1, MAPK9, MAPK14, and CREBBP were identified as host’s infection response regulators of bacterial Hcp in duck." (PMID 36262184, 2022). "For instance, the upregulation of MAPK14 and MAPKAAPK2 could explain the upregulation of MAPK signalling pathways observed after infection with MA08." (PMID 34671358, 2021). "Quantitative real time PCR (qRT-PCR) of RNA in SCC-25 cells after 24 h of infection with P. gingivalis total membrane showed statistically significant up-regulation of the following genes: IκBκB (4.7 ×), MAP2K4 (4.6 ×), MAPK14 (4.2 ×) and IRF5 (9.8 ×) (p < 0.01) (n = 9)." (PMID 28056810, 2017). "By repressing the expression of MAPK14 and BID via miRNAs, HCV may be able to hinder apoptosis before ensuring successful establishment of virus replication at an early stage of infection." (PMID 19671175, 2009). "The upregulation of MAPK14 in the IAV-S infected pigs, however, is likely the result of the acute nature of the virus and host induction of the pro-inflammatory cytokines to produce an antiviral environment within the respiratory tract during the early stages of infection." (PMID 32033425, 2020). "In addition, genes that targeted kinases (MAP2K7, MAP4K4 and MAPK14) were downregulated in the first 15 min of CHIKV infection, although MAP2K7 and MAP4K4 were subsequently found to be upregulated after 30 min and 120 min of infection." (PMID 23409203, 2013).
neurodegenerative disease (9 papers, 2010 to 2024). A disorder of the central nervous system characterized by gradual and progressive loss of neural tissue and neurologic function. "The pathologies of all these neurodegenerative diseases have been associated with the activation of MAPK14/p38 and inhibition of the kinase had beneficial effects on the course of the disease." (PMID 36298696, 2022). "Importantly, all of these synaptic regulators (Nos1, Lrp8, Argef2, Sema5b) and other significantly altered splice variants (e.g., Adipor2, Mapk14, Smarca4, Sort1, Mapt) have been linked to AD and other neurodegenerative diseases." (PMID 37819053, 2023). "The MAPK14 activation disrupts the autophagosome-lysosome fusion, impairing autophagy, with implications for the neurodegenerative diseases like AD and PD." (PMID 39469068, 2024). "Key to these pathways are the evolutionarily conserved mitogen-activated protein kinases (MAPKs); of these, p38-MAPK (also known as MAPK14) has received considerable attention as potential therapeutic target for inflammatory and degenerative diseases such as OA." (PMID 20955562, 2010).
neurological disorders (4 papers, 2023 to 2024). "MAPK14 is an important player in a variety of nervous system diseases, and contributes to the control of cerebrovascular and blood-brain barrier." (PMID 36969199, 2023). "MAPK14, a member of the MAP kinase family, is involved in various neurological diseases, particularly affecting autophagy." (PMID 39469068, 2024).
breast (3 papers, 2020 to 2022). "MAPK14, a member of the p38 subfamily, was known to regulate inflammatory cytokines, and exerted an essential role in inflammatory acute lung injury." (PMID 35350754, 2022).
infectious disease (2 papers, 2018 to 2020). A disorder directly resulting from the presence and activity of a microbial, viral, or parasitic agent in humans. "Herbal medicine probably controls the infectious disease mainly based on immunomodulatory agents stimulation (such as GSK3B, MAPK14, PPARγ) will probably help innate and adaptive immune, and regulation the inflammatory cytokines and proinflammatory mediators (like IL-6, IL-8, TNF-α, COX2)." (PMID 29301573, 2018).
respiratory diseases (1 paper, 2024). "Virtual screening and PIN indicated that naringin, chryso-obtusin glucoside, and rubrofusarin-6-O-β-D-gentiobioside were the main active compounds from CGE interacted with MAPK14 and MMP9, which provides the key mechanism of CGE for the treatment of respiratory diseases." (PMID 38974913, 2024).
MAPK14 also shares sentences with these, for which no sentence is quoted: Hyperglycemia (20 papers); cardiac hypertrophy (11); renal fibrosis (7); bacterial infection (5); cardiovascular diseases (5); diabetic neuropathy (5); Hypertension (5); ischemia (5); myeloma (5); periodontitis (5); bladder cancer (4); Cognitive impairment (4); endothelial dysfunction (4); inflammation (4); pemphigus (4); Cerebral ischemia (3); chronic myelogenous leukemia (3); immune disease (3); kidney disease (3); metabolic disorders (3); Myocardial fibrosis (3); neuropathy (3); sarcopenia (3); SARS-CoV infection (3); skin inflammation (3); abortion (2); acute kidney injury (2); acute lung injury (2); adenocarcinoma (2); anaplastic large cell lymphoma (2).
A further 143 diseases each share a sentence with MAPK14 in 2 papers or fewer.